TNF (tumor necrosis factor)
Diseases named in the same sentence as TNF in open-access papers (continued):
Sharing a sentence is not in itself a finding about the gene and the disease.
colorectal cancer (continued). "In human colorectal carcinoma tumors sTNFR1 was shown to be significantly upregulated compared to normal colon tissue, contributing to the insensitivity to apoptosis by TNF-α." (PMID 39200479, 2024). "Overall, these data and data regarding cell migration show that inhibition of Pol III activity blocks TNFα-induced EMT in colorectal cancer cells." (PMID 36900285, 2023). "In terms of miR-139-5p role in inflammation, overexpression of miR-139-5p was found to inhibit MMP9, MMP7, cell proliferation, and pro-inflammatory cytokines (IL-1β, IL-6, TNF-α) in colorectal cancer cell lines." (PMID 37474869, 2023). "We observed that TNF-α, at concentrations reported to be present in serum and tumour tissue from colorectal cancer patients, upregulated miR-21 expression in both cell lines." (PMID 36765584, 2023). "Interleukin-6 and tumour necrosis factor alpha (TNFα) are cytokines considered to be important players in colorectal cancer development and progression." (PMID 36900285, 2023). "On the other hand, miR-34a acts as an immunosuppressive miRNA in colorectal cancer via regulation of SIRT1/NF-κB/B7-H3/TNF-α axis." (PMID 37441551, 2023). "At the tumor level, in colorectal cancer, TNF-α induces DNA instability and, by binding to its receptor, like IL-1β, activates the oncogenic signaling pathways, especially NF-kB and Wnt, proving the strong oncogenic role of this cytokine." (PMID 38137862, 2023). "In the orthotopic transplant model, the administration of anti-TNFα mAb led to a reduction in colorectal cancer." (PMID 36996146, 2023). "Results of experiments performed with mice orthotopically transplanted with colorectal cancer cells and treated with anti-TNFα mAb." (PMID 36996146, 2023). "The current study shows that treating colorectal cancer cells with ML-60218 augments prototypical functions of TNFα." (PMID 36900285, 2023). "Here, we report mechanistic evidence that supports a relationship between the pro-inflammatory cytokine TNF-α and miR-21 in the progression of colorectal cancer epithelial cells towards a metastatic phenotype." (PMID 36765584, 2023). "It has been reported that TNFα enhances the migration of cancer cells, including colorectal cancer cells." (PMID 36900285, 2023). "In particular, our previous studies have identified the strong association of inflammatory mediators with the progression of colorectal cancer and the ability of TNF-α to promote DNA damage in colorectal cancer cells." (PMID 36765584, 2023). "In colorectal cancers, PRKCDBP induction by TNF‐α was confirmed to be disrupted when NF‐κB signalling was blocked, and previous research revealed PRKCDBP is implicated in TNF‐α‐induced apoptosis." (PMID 36696967, 2023). "Patients administered with DEX in colorectal cancer surgery also had better cardiocerebral protection with a reduced expression level of serum TNF-α." (PMID 36765695, 2023). "Compared with homologous RBC transfusion, autologous RBC transfusion was reported to alleviate transfusion-related immunosuppression by increasing the plasma TNF-α level in esophageal and colorectal cancer patients undergoing radical resections." (PMID 36765695, 2023). "We investigated the molecular mechanisms by which antrodin C induces cell apoptosis via the ROS and AKT/ERK/P38-pathway-mediated epigenetic histone H3K9K14ac of TNFα in colorectal cancer cells (CRCs)." (PMID 36979011, 2023). "miR-19a can induce EMT under the upregulation of TNF-α, thus promoting colorectal cancer (CRC) invasion and metastasis." (PMID 37369681, 2023). "Anti-TNFα mAb acts as an inhibitor of tumor progression in the tumor microenvironment of a colorectal cancer orthotopic transplant mouse model." (PMID 36996146, 2023). "For instance, through activation of NF-κB signaling pathway, PKM2 is critical for the production of TNF-α and IL-1β in colorectal cancer." (PMID 36797689, 2023).
colorectal cancer (continued). "Previous studies have also shown that saffron treats diseases through the HIF-1α/VEGF signaling pathway, and crocin inhibits angiogenesis and metastasis of colorectal cancer cells by targeting NF-κB and blocking the TNF-α/NF-κB/VEGF pathway." (PMID 37959658, 2023). "TNF-α promotes epithelial-–mesenchymal transition by stimulating the CXCL10/CXCR3 axis of colorectal cancer cells." (PMID 37048082, 2023). "Modulating the NOD2/TNF-α signaling axis to balance the induction of mo-DCs and repression of mo-Macs appears to be a promising new target for immunotherapy of colorectal cancer and to treat stricturing complications of CD patients." (PMID 37415975, 2023). "Previous studies have reported elevated levels of several circulating cytokines in colorectal cancer patients, including IL-1β, IL-8, and TNF-α, which are thought to promote tumor development in the context of chronic inflammation." (PMID 37063892, 2023). "During the laparoscopic radical resection of colorectal cancer, the addition of a single subanesthetic dose of ketamine was also reported to decrease the plasma level of TNF-α, prevent brain injury, and improve postoperative fatigue syndrome." (PMID 36765695, 2023). "Our data indicate that exposing colorectal cancer epithelial cells to TNF-α, at concentrations occurring in the serum and tumour microenvironment of colorectal cancer patients, upregulated miR-21 expression and promoted the metastatic phenotype." (PMID 36765584, 2023). "We investigated the relationship between TNF-α and microRNA-21 in colorectal cancer cells and show their involvement in promoting cell changes indicative of the metastatic state." (PMID 36765584, 2023). "In this study, we investigated the relationship between TNF-α and miR-21 regulation in colorectal cancer epithelial cells (SW480 and HCT116)." (PMID 36765584, 2023). "5,7-DMC suppresses the production of IL-1β, TNFα and IL-8 in the colorectal carcinoma HT-29 cell line." (PMID 37920212, 2023). "It has recently shown that TNF-α stimulates the expression of miR-105 and this miRNA stimulates the invasion and metastasis of colorectal cancer cells." (PMID 35410210, 2022). "In summary, levels of IL-6, TNF-α and IL-12P7 in plasma of patients with advanced colorectal cancer increased." (PMID 36226059, 2022). "Our study finding was consistent with the previous studies, which suggested a protective effect of TNF inhibition on colorectal cancer." (PMID 36618924, 2022). "Multi-factor analysis of the influencing factors of the TNF-α level in patients with colorectal cancer." (PMID 36226059, 2022). "Downregulation of IFN-γ and TNF-α, along with the upregulation of IL-6 and IL-8, has been observed in colorectal cancer." (PMID 36035429, 2022). "It inhibits the IL-6 cellular pathway and suppresses the expression of TNF, which has therapeutic effects on mouse colorectal cancer models." (PMID 36193082, 2022). "Fusobacterium induced inflammation through TNF-α and NF-κB in an in vitro cultured colorectal cancer cell line." (PMID 35633706, 2022). "We started with the evaluation of levels of IL-6, TNF-α and IL-12P7, and observed that IL-6 levels are associated with lymph node metastasis and the TNM staging in patients with colorectal cancer (t = 6.705, -4.224, P <0.05)." (PMID 36226059, 2022). "The aim of the study was to analyze the salivary concentrations of chemerin, α-defensin 1, and TNF-α in colorectal cancer (CRC) patients and in a healthy control group." (PMID 36005576, 2022). "On the other hand, knockdown of human miR-375 upregulates NF-κB and pro-inflammatory factors, such as tumor necrosis factor-α, IL-1β, IL-6 and IL-8, in the colorectal cancer cell line Caco-2." (PMID 35052815, 2022). "In conclusion, our drug-target mendelian randomization study showed a protective effect of anti-TNF on colorectal cancer." (PMID 36618924, 2022).
colorectal cancer (continued). "In a mouse model of colitis-associated colorectal cancer, a membrane protein isolated from Akkermansia muciniphila delayed tumor growth and decreased tumor number and size by boosting CD8+ T cells and TNF- production in the colon." (PMID 36140470, 2022). "In this study, we found that roburic acid treatment significantly inhibited the TNF-induced phosphorylation of IKKα/β, IκBα, and p65, degradation of IκBα, and nuclear translocation of p65 in human colorectal cancer cells." (PMID 35222445, 2022). "We used the search terms “TNF”, “TNF receptor”, “TNFR1”, “TNF inhibition”, “TNF monoclonal antibodies”, and “colorectal cancer”." (PMID 36618924, 2022). "Blocking TNFα in mice subjected to DSS and AOM-DSS protocols prevents mucosal ulcer development and reduces colorectal cancer associated with chronic colitis." (PMID 35804854, 2022). "Our results show that the IL-6 levels of patients with neutral colorectal cancer in late clinical staging were higher (P <0.05) and the TNF-α levels of patients with low division were higher (P<0.05)." (PMID 36226059, 2022). "Collectively, these results indicated that roburic acid inhibits TNF-induced NF-κB signaling in colorectal cancer cells." (PMID 35222445, 2022). "The results indicated that roburic acid is a novel TNF-targeting therapeutics agent in colorectal cancer as well as other cancer types." (PMID 35222445, 2022). "For example, serum TNF‐α, IL‐1β, IL‐6, and IL‐8 are positively associated with elevated HADS score in colorectal cancer patients." (PMID 34697903, 2022). "According to the findings obtained from combined treatment of resveratrol and 5-FU, it was found that resveratrol reduces phosphorylated NF‐κB, IκBα, and IKK levels as well as MMP-9, COX-2, IL-6, and TNF-α levels in colorectal cancer cells." (PMID 35366874, 2022). "Recently, it has become clear that TNF-induced NF-κB signaling also plays a critical role in colorectal cancer development and progression, and is a potential therapeutic target for the treatment of these conditions." (PMID 35222445, 2022). "This miRNA can reduce the expression of IL-6 and TNF-α in colorectal cancer cells, possibly by suppressing NFκB signaling." (PMID 35410210, 2022). "SAA expression was promoted by IL-22 in normal mouse cells, by lipopolysaccharide (LPS) in mouse colorectal cancer cell lines, as well as by a combination of IL-1ß, IL-6, and tumor necrosis factor-α (TNF-α) in human colorectal cancer cell lines." (PMID 35303008, 2022). "Another study showed that the experimental blockage of TNF-α limits the development of colitis and colorectal cancer, and the gut microbial profile of such mice was different from that of the normal counterpart." (PMID 35625485, 2022). "In the AOM/DSS model of colorectal cancer, probiotic introduction reduced the tumor burden via modulation of the immune response, including reduced TNF levels." (PMID 33917839, 2021). "In colorectal cancer, the production of IL-17 and TNF-α favors the recruitment of PMN-MDSCs and total MDSCs, promoting colorectal cancer (CRC) development and progression, and IL-17 leads to the accumulation of neutrophils in the colon." (PMID 34299314, 2021). "For example, the inflammatory cytokines TNFα and IL-17 enhance PD-L1 expression in colorectal cancer through activation of Akt, NF-κB, and ERK1/2 signaling." (PMID 33406733, 2021). "According to the KEGG database, the genes in module 5 were mainly enriched in the TNF signaling pathway, glutathione metabolism, cytokine-cytokine receptor interaction, hepatocellular carcinoma, colorectal cancer and focal adhesion, among others." (PMID 34301206, 2021). "More recently, britannin was recognized to exhibit anti-colorectal cancer effects via downmodulating TNF-induced PD-L1 expression." (PMID 34575983, 2021).
colorectal cancer (continued). "The results of numerous studies in the last decade have shown that transforming growth factor-beta (TGF-β) and tumor necrosis factor-α (TNF-α) play pivotal roles in the formation of EMT in colorectal cancer." (PMID 34094030, 2021). "Britannin interrupts mTOR signaling and inhibits MYC proto-oncogene (MYC), as well as HIF-1α expression in TNF-treated colorectal cancer cells." (PMID 34575983, 2021). "Fusobacterium and F. nucleatum abundance in colonic mucosa have been found to be significantly more abundant in patients with adenoma and colorectal cancer, and these bacteria have the capacity to induce severe TNF-mediated inflammation." (PMID 34336979, 2021). "On the one hand, colorectal cancer cell-derived versican promoted the polarization of macrophages toward the pro-inflammatory M1 phenotype with up-regulated release of IL-6, IL-12 and TNF-α." (PMID 33466303, 2021). "Colorectal cancer-derived TNFα facilitates tumor growth and TAM recruitment, in turn, inducing TAM-mediated secretion of autocrine CSF1." (PMID 33406733, 2021). "Previous studies demonstrated a pro-tumorigenic effect of TNF in a mouse model of chemically induced colorectal cancer." (PMID 33917839, 2021). "The increase of proinflammatory factors, including IL-1β, TNF-α, and IL-6, will aggravate intestinal inflammation and promote the occurrence of colorectal cancer." (PMID 34594475, 2021). "In a randomized double-blind placebo-controlled trial of probiotics in the post-surgical period of colorectal cancer, a reduction in intestinal inflammation and production of pro-inflammatory cytokines, including TNF, were reported." (PMID 33917839, 2021). "TNF- α increased levels of pro-inflammatory cytokines, such as IL-6 and IL-8 in vitro on HT-29 colorectal cancer cells." (PMID 34631734, 2021). "Curcumin has also been established to be effective in people suffering from colorectal cancer, and it was observed that it decreased the level of serum Tumor necrosis factor (TNF-α), as well as increased the apoptosis and also improved the overall health." (PMID 34443593, 2021). "In particular, TNF is increased in serum and in exhaled breath condensate of lung cancer patients, as well as in serum of patients with colorectal cancer and in different types of leukemia." (PMID 33917839, 2021). "The expression of TNF-α is much higher in colorectal cancer than in adjacent normal colorectal tissue." (PMID 34631734, 2021). "In colorectal cancer, F. nucleatum promotes a NF-κB-driven proinflammatory genetic signature, including tumor necrosis factor (TNF) and interleukin-6 (IL-6) gene expression, cytokines that are also important in intestinal inflammation." (PMID 33653893, 2021). "A 12-week home-based exercise program also reported a significant decrease in the expression of TNF-α in colorectal cancer patients." (PMID 32309219, 2020). "Andrographolide reduces the activation of AP-1 in human colorectal cancer and endothelial cells, induced by TNF-α." (PMID 33374961, 2020). "In fact, andrographolide inhibits Src and ERK1/2, interfering with the activation of AP-1 and antagonizing TNF-α-induced IL-8 in HCT116 human colorectal cancer cells." (PMID 33374961, 2020). "Trans-nerolidol exhibited anticancer effects in colorectal cancer cells through the induction of apoptosis in the presence of tumor necrosis factor (TNF) α." (PMID 32708138, 2020). "For instance, TNF-α suppresses the expression of CLDN4 in colorectal cancer, and the level of TNF-α is increased by Clostridium perfringens type A enterotoxin (CPE)." (PMID 32064037, 2020). "miR-19a overexpression is correlated with lymph node metastasis and participates in tumor necrosis factor (TNF)-α-induced EMT in colorectal cancer." (PMID 32984321, 2020). "In recent years, TNF-α modified by asparagine glycine arginine (NGR) is used to treat colorectal cancer, liver cancer and malignant pleural mesothelioma." (PMID 32552897, 2020).
colorectal cancer (continued). "Carcinogenic effects have been suggested by a clinical study of 30 colorectal cancer patients in which the TNF gene was significantly overexpressed in cancerous tissue compared with adjacent normal colorectal tissue." (PMID 32805626, 2020). "High levels of TNF-α have been described in several studies among patients suffering from cancer, including gastric carcinoma, colorectal carcinoma, hepatocellular carcinoma, head and neck cancer." (PMID 32592356, 2020). "For instance, it has been reported that TNF-α has elevated expression in colorectal cancer tissue compared with normal colorectal tissue, and that cancer tissues in advanced stages have higher TNF-α expression compared with cancer tissues in earlier stages." (PMID 30600678, 2019). "In our clinical trial, circulating inflammatory cytokines of TNF-α, IL-10, IL-12, IL-17A, IL-17C and IL-22 remained high in colorectal cancer patients even after removal of tumor." (PMID 31340751, 2019). "In colorectal cancer, the pro-inflammatory cytokines TNFα and IL-17 have been reported to cooperatively stimulate glycolysis." (PMID 31655629, 2019). "Patients who suffer from colorectal cancer exhibit high serum levels of inflammatory mediators such as IL-1β, IL-6, TNF-α and PGE227,28." (PMID 31511625, 2019). "It has been confirmed that TNF-α expression levels have a positive correlation with Dukes’ stages, and that TNF-α mRNA transcripts are higher in colorectal cancer (CRC) cells than normal epithelial colon cells." (PMID 29467927, 2018). "Four CRC cell lines were used to investigate the potential inhibitory effect of KLT on TNF-α induced cell invasion and migration in colorectal cancer." (PMID 29467927, 2018). "For example, enhanced abundance of TNFR2+ Treg and high TNFα serum level were reported in patients with ovarian cancer, lung cancer as well as colorectal cancer." (PMID 29619032, 2018). "It was previously recorded that the upregulated expression of miR‐19a in colorectal cancer cell responded to TNF‐α stimulation‐mediated TNF‐α‐induced epithelial‐to‐mesenchymal transition of the tumour cell." (PMID 29632814, 2018). "Inflammation and pro-inflammatory cytokines produced by Th1 and Th17 cells like IL-6, TNF, IL-17 and IL-23 promote the development and growth of colorectal cancer (CRC)." (PMID 28881611, 2017). "Our tentative experiments indicated that TNF-α inhibitor had an anti-tumor effect against colorectal cancer, although further studies still need to be carried out." (PMID 29238068, 2017). "A retrospective analysis of 40 colorectal cancer patients revealed a potential beneficial effect of TNF-α by showing that increased TNF-α concentration in the sera correlated with improved survival." (PMID 29069789, 2017). "We genotyped four polymorphisms in four genes (IL1B, TNF, PPARG, and PPARGC1A) and calculated the dietary inflammatory index (DII) in a case-control study with 701 colorectal cancer patients and 1,402 controls." (PMID 28051997, 2017). "Meanwhile, TNF-α can induce epithelial mesenchymal transformation and subsequently promotes the invasion and metastasis of colorectal cancer." (PMID 28575042, 2017). "As TRAP1’s full name, tumor necrosis factor receptor-associated protein 1 implies, TNF-α promotes tumor invasion via induction of matrix metalloproteinases, and finally modulates EMT in a model of colorectal cancer." (PMID 28088229, 2017). "Finally, our pharmacogenetics studies of gene-environment interactions in relation to development of colorectal cancer, suggest that intake of red and processed meat interacts with genes encoding TLRs and NF-κB, which may offer a potential link to anti-TNF treatment response." (PMID 28294972, 2017). "Due to the ability of inducing growth factors and suppressing apoptosis, TNF-α or activation of NF-κB pathway is required for the progression of hepatocellular carcinoma and colorectal cancers." (PMID 26910375, 2016).